BMPR1B (bone morphogenetic protein receptor type 1B)
Description:
On ligand binding, forms a receptor complex consisting of two type II and two type I transmembrane serine/threonine kinases. Type II receptors phosphorylate and activate type I receptors which autophosphorylate, then bind and activate SMAD transcriptional regulators. Receptor for BMP7/OP-1 and GDF5. Positively regulates chondrocyte differentiation through GDF5 interaction.
Synonyms: CDw293; ALK6; ALK-6; AMD3; AMDD; BDA1D; BDA2
Tractability: Small molecule: a structure with a bound ligand is known; a high-quality ligand is known; it belongs to a druggable protein family. Antibody: UniProt places it where antibodies can reach, with high confidence; its Gene Ontology location is reachable by antibodies, with high confidence; UniProt predicts a signal peptide or a membrane-spanning region. PROTAC: ubiquitination databases record sites on it; a small molecule that binds it is known. Other modalities: an approved drug acts on it.
Target class: Enzyme; TKL protein kinase group; TKL protein kinase STKR family; TKL protein kinase STKR Type 1 subfamily; Protein Kinase; Kinase
Gene: Protein-coding gene on chromosome 4 (94,757,937 to 95,158,448, forward strand). Ensembl gene ENSG00000138696.
Subcellular location: Cell membrane
Pathways (Reactome):
Signal Transduction: Signaling by BMP
Gene Ontology:
Molecular function: ATP binding; BMP binding; BMP receptor activity; protein binding; protein serine/threonine kinase activity; SMAD binding; transmembrane signaling receptor activity; transforming growth factor beta receptor activity, type I; transmembrane receptor protein serine/threonine kinase activity; protein kinase activity
Biological process: BMP signaling pathway; cellular response to BMP stimulus; osteoblast differentiation; positive regulation of bone mineralization; positive regulation of gene expression; positive regulation of osteoblast differentiation; positive regulation of transcription by RNA polymerase II; cell differentiation; cellular response to growth factor stimulus; chondrocyte development; dorsal/ventral pattern formation; endochondral bone morphogenesis; eye development; negative regulation of chondrocyte proliferation; ovarian cumulus expansion; ovulation cycle; positive regulation of cartilage development; positive regulation of chondrocyte differentiation; proteoglycan biosynthetic process; bone development; cell surface receptor protein serine/threonine kinase signaling pathway; chondrocyte differentiation; inflammatory response
Cellular component: plasma membrane; HFE-transferrin receptor complex; receptor complex; membrane
Genetic constraint (gnomAD): Loss-of-function variants: 12 observed, 58.65 expected, observed/expected ratio (o/e) 0.2, 90% interval 0.13 to 0.33. The upper end of that interval is the gene's LOEUF score, 0.33, which puts it in group 1 of 6, group 1 being the genes least tolerant of losing a copy. Missense variants: 543 observed, 630.13 expected, observed/expected ratio (o/e) 0.86, 90% interval 0.8 to 0.93. Synonymous variants: 236 observed, 216.05 expected, observed/expected ratio (o/e) 1.09, 90% interval 0.98 to 1.22.
Gene-disease validity (ClinGen):
ClinGen rates the evidence that BMPR1B causes each of these diseases.
pulmonary arterial hypertension (inheritance undetermined): Disputed. Pulmonary arterial hypertension (PAH) is a group of diseases characterized by mean pulmonary artery pressure >20 mmHg and elevated pulmonary arterial resistance leading to right heart failure.
Homologues: Orthologues: chimpanzee BMPR1B (99% identical), macaque BMPR1B (99% identical), guinea pig BMPR1B (99% identical), rabbit BMPR1B (99% identical), dog BMPR1B (98% identical), mouse Bmpr1b (98% identical), pig BMPR1B (98% identical), rat Bmpr1b (98% identical), tropical clawed frog bmpr1b (90% identical), zebrafish bmpr1ba (82% identical), zebrafish bmpr1bb (79% identical), Drosophila melanogaster tkv (52% identical), and 1 more. Paralogues in human: BMPR1A (72% identical), TGFBR1 (52% identical), ACVR1B (49% identical), ACVR1C (48% identical), ACVR1 (48% identical), ACVRL1 (44% identical), ACVR2A (30% identical), ACVR2B (28% identical), BMPR2 (27% identical), TGFBR2 (27% identical), AMHR2 (25% identical).
Diseases named in the same sentence as BMPR1B in open-access papers:
BMPR1B is named in the same sentence as 79 diseases in open-access papers, as found by Europe PMC text mining. Sharing a sentence is not in itself a finding about the gene and the disease. The quoted sentences say what the papers report.
breast carcinoma (14 papers, 2011 to 2023). "It has been reported that reduced expression of BMPR1B can increase the proliferation of breast cancer cells, and is also associated with poor prognosis and bone metastasis in breast cancer patients." (PMID 34090364, 2021). "The target site contains a SNP, rs1434536, that is in linkage disequilibrium with two high scoring markers in a breast cancer association study and results in disruption of the regulation of BMPR1B by miR-125b." (PMID 23091610, 2012). "It suggests that other regulatory mechanisms exist in the ER positive breast cancer cells to maintain the expression of BMPR1B." (PMID 37333824, 2023). "Next, we investigated functions of BMPR1B gene in breast cancer cells with different phenotypes including MCF-7 (luminal type), SKBR3 (HER2 + type) and MDA-MB-231 (triple-negative breast cancer) by stably overexpressing BMPR1B gene." (PMID 37644609, 2023). "In four main subtypes of breast cancer, elevated expression of BMPR1B and ACVR2B were seen in Luminal A subtype, while BMP4, GDF15 and ACVR1B were higher in Luminal B, TGFBR1 and BMP8A were higher in HER2 positive, BMP2, BMP6 and GDF5 were higher in TNBC." (PMID 37333824, 2023). "Further, expression of BMPR1B enhances cancer cell migration, and approaches targeting BMPR1B inhibit metastatic activity in breast cancer." (PMID 32697766, 2020). "Reduced expression of BMPR1B has previously been found to be correlated with poor prognosis in breast cancer." (PMID 32714600, 2020). "Down-regulation of BMPR1B expression was recently reported in malignancies such as epithelial ovarian cancer, gliomas, and breast cancer, correlating with poor prognosis in such patients." (PMID 24339876, 2013). "Our luciferase assay confirmed more effective posttranscriptional repression through BMPR1B 3'UTR containing the major C allele in endometrium cell lines, as compared to previous assay performed in breast cancer cell lines." (PMID 24339876, 2013). "A previous miRNA microarray study reported nearly a two-fold increase of miR-125b in ectopic endometrial tissue, and reduced BMPR1B expression was also found to promote proliferation of breast cancer cells." (PMID 24339876, 2013). "Decreased expression of Bmpr1b predicts poor prognosis in breast cancer patients and leads to increased cell proliferation of breast cancer cells in vitro, suggesting the tumor suppressor role of the Bmpr family in breast cancer carcinogenesis." (PMID 21846369, 2011). "We found that BMPR1B overexpression could enhance the malignant biological behaviors of MCF-7 breast cancer cells in both in vitro and in vivo experiments, suggesting that the interface zone possesses some characteristics like the tumor zone." (PMID 37644609, 2023). "However, a reduction in BMPR1B expression induced tumor proliferation in breast cancer." (PMID 37373155, 2023). "Moreover, reduction of BMPR1B mRNA level by miR-125b-wt was much stronger compared to the mRNA suppression in breast cancer cells, suggesting expressional regulation exerted by miR-125b as more predominant in endometrial tissue, possibly due to tissue-dependent variation of endogenous miRNA levels." (PMID 24339876, 2013). "In summary, a shift in the expression pattern of BMPs in breast cancer, including increased BMP8A, BMPR1B and decreased BMP6, BMP7, ACVR1C, TGFBR2, TGFBR3 and BMPR2 presented a subtype specific role." (PMID 37333824, 2023). "BMPR1B and ACVR2B were positively correlated with ER in Luminal A subtype (ER+, HER2-) breast cancer." (PMID 37333824, 2023).
breast carcinoma (continued). "Furthermore, higher levels of BMP2, BMP6 and GDF5 were revealed in triple negative breast cancer (TNBC) whilst BMP4, GDF15, ACVR1B, ACVR2B and BMPR1B were relatively higher in Luminal type BC." (PMID 37333824, 2023). "Genetic alterations in BMPR1A, BMPR1B, or BMPR2 were found in around 6, 7, or 5% of patients with breast cancer, respectively, with the major form of genetic alternation being an upregulation of mRNA encoding BMP receptors (data not shown)." (PMID 31409851, 2019). "When queried for the three most common BMP receptors: BMPR1a, BMPR2 and BMPR1b, BMPR1a and BMPR2 are largely equally distributed for high and low expression between the four largest molecular subtypes of breast cancer." (PMID 26274893, 2015). "We have previously reported that all six BMP specific receptors (ACVR1, BMPR1A, BMPR1B, ACVR2A, ACVR2B, and BMPR2) are uniformly expressed among the breast cancer cell lines studied here." (PMID 22118688, 2011). "Only BMPR1b shows a bias to be downregulated in basal type breast cancers and no other subtype." (PMID 26274893, 2015).
glioblastoma (8 papers, 2013 to 2022). The most malignant astrocytic tumor (WHO grade IV). "Glioblastoma CSCs display some similarities with early embryonic NSCs; for example, they both lack BMPR1B expression and have a temporary response to BMP ligands." (PMID 28415635, 2017). "A deregulated BMPR1B pathway in a subset of glioblastoma cells contributes to their tumorigenicity by desensitizing the cells to normal differentiation cues and by converting cytostatic signals into pro-proliferative signals." (PMID 29326596, 2017). "EZH2 is essential for glioblastoma cancer stem cell maintenance, blocks astroglial differentiation and promotes glioma tumorigenensis by repressing BMPR1B and BMPR1B-mediated differentiation signaling." (PMID 25831237, 2015). "The hypermethylation of this region silences BMPR1B expression in human glioblastoma tumor-initiating cells and results in inhibition of normal cell differentiation and subsequent tumorigenicity." (PMID 26228095, 2015). "BMPR1B was also shown to be down-regulated in about 20% of primary glioblastoma tumours, and this is correlated with increased promoter DNA methylation." (PMID 22771539, 2013). "EZH2-dependent epigenetic silencing of the BMP receptor 1B (BMPR1B) in a subset of glioblastoma tumour-initiating cells (TICs) has also been noted, thereby limiting the extent to which the TICs can respond to differentiation signals." (PMID 22771539, 2013). "In the animal model system, the over expression of BMPR1B significantly inhibited the tumorigenicity of glioblastoma cells, while the decreased expression of BMPR1B significantly enhanced the tumorigenicity of glioblastoma cells." (PMID 33116227, 2020). "Epigenetic silencing of BMPR1B was reported in a subset of glioblastoma cells." (PMID 29326596, 2017). "Histone modification by polycomb repressive complex 2, through its catalytic subunit EZH2, induces the epigenetic silencing of the BMPR1B/ALK6 gene, leading to escape from the BMP‐induced differentiation of glioblastoma cells." (PMID 34214250, 2022).
brachydactyly (7 papers, 2017 to 2025). A disease characterized by the presence of brachydactyly, including syndromic and non-syndromic forms. "Previous studies reported the presence of BMPR1B mutations in patients with human joint fusion and limb deformities, including brachydactyly type A2, brachydactyly type C/symphalangism-like phenotype, and du Pan acromesomelic dysplasia." (PMID 28418932, 2017). "Similarly, case reports demonstrate that CBHV occurs in brachydactyly type 2A, brachydactyly type C/symphalangism and in patients with isolated BMPR1B variants." (PMID 38879467, 2024). "For example, we identified putative enhancers of BMPR1B and IHH (both genes are associated with brachydactyly type-A, OMIM #112500), and candidate enhancers of RUNX2, a gene linked to cleidocranial dysplasia, with brachydactyly (OMIM #119600)." (PMID 35896673, 2022).
glioma (7 papers, 2012 to 2020). A benign or malignant brain and spinal cord tumor that arises from glial cells (astrocytes, oligodendrocytes, ependymal cells). "The effect of BMP2 on glioma differentiation and apoptosis is receptor dependent, which mainly depends on the receptor BMPR1B." (PMID 33116227, 2020). "The overexpression of BMPR1B activated the BMPs/Smad1/5/8 signaling pathway and inhibited the growth of glioma cells through various mechanisms, including the decrease of SKP2 expression, followed by the increase of p21 and p27kip1 Protein Expression35." (PMID 33116227, 2020). "The expression of BMP2 and BMPR1B are different in different types of gliomas, and their different combinations lead to different prognosis of different types of gliomas." (PMID 33116227, 2020). "A new glioma grade (HB grade) based on histopathology and BMP2 expression can predict the prognosis of glioma patients, with BMPR1B and BMPR2 expression indicating a different prognosis in different types of gliomas." (PMID 33116227, 2020). "In addition, miR-125b contributes to ovarian granulosa cell apoptosis by targeting BMPR1B, and its expression affects the proliferation and apoptosis of human glioma cells by targeting Bmf." (PMID 31394878, 2019). "Both BMP type IA (BMPR-1A) and the type IB (BMPR-1B) receptors were detected in human glioma cells." (PMID 23998913, 2013). "Epigenetic silencing of BMPR1B in a subset of gliomas leads to astroglial differentiation block." (PMID 23998913, 2013). "In the company of low BMPR1B expression, BMP2 increased the differentiation and apoptosis of glioma in a concentration dependent manner." (PMID 33116227, 2020).
chondrodysplasia (6 papers, 2013 to 2025). "We extend the genotype-phenotype correlation in the acromesomelic chondrodysplasias by showing that the milder du Pan dysplasia can be caused by a hypomorphic BMPR1B mutation." (PMID 26105076, 2015).
acromesomelic dysplasia (5 papers, 2015 to 2024). A group of extremely rare, inherited, progressive skeletal conditions that result in a particular form of short stature, called short-limb dwarfism. "Homozygous pathogenic variants of BMPR1B can cause acromesomelic dysplasia with malformations in the genital tract." (PMID 38879467, 2024). "Finally, inactivating mutations in BMPR1B (ALK6) result in uncommon inherited skeletal disorders, named acromesomelic dysplasias (AMD), which are characterized by short stature, extremely short limbs, and deformities in the hands and feet." (PMID 37681932, 2023). "Likewise, BMPR1B, a member of the bone morphogenetic protein (BMP) receptor family of transmembrane serine/threonine kinases, which belongs to the transforming growth factor (TGF)-β superfamily, was reported to be associated with acromesomelic dysplasia." (PMID 31699087, 2019).
breast tumors (4 papers, 2013 to 2023). "To elucidate the association of BMPR1B with endometriosis, we performed genetic and functional study of SNPs within and next to the mir-125b binding site on BMPR1B, previously identified as genetic risk factors of estrogen receptor-stratified breast tumors in a genome-wide association study." (PMID 24339876, 2013). "That study reported lower levels of BMPR1B expression in breast tumour samples compared with normal breast tissue samples, as well as reduced BMPR1B mRNA in samples taken from patients with predicted poor prognosis." (PMID 32714600, 2020). "In addition, we found that the proliferative luminal cells (KI67 +) in the interface zone of HER2 positive breast tumors highly expressed the BMPR1B gene and may develop into cancer cells in this specific microenvironment." (PMID 37644609, 2023). "ACVR1C, TGFBR2, TGFBR3, ACVR2A, ACVR1, BMPR1A and BMPR2 were lower in breast tumours while ACVR1B and BMPR1B exhibited relatively higher expression levels in paired tumours compared with normal breast tissues, in the TCGA_BRCA cohort." (PMID 37333824, 2023).
endometriosis (3 papers, 2013 to 2020). The growth of functional endometrial tissue in anatomic sites outside the uterine body. "Our previous study showed that a miR-125b binding site variation at the 3′-UTR of BMPR1B defines endometriosis susceptibility and CA125 levels." (PMID 26285705, 2015). "Though increase of BMPR1B in endometriosis epithelium cells is subtle via variants in the miR-125b binding site, predominant BMPR1B expression in stroma cells seems sufficient to suppress CA125 production by neighboring epithelium cells." (PMID 24339876, 2013). "Within samples with homozygous variant allele, more abundant BMPR1B appeared in endometriosis tissues, while the corresponding CA125 expression profoundly diminished in both epithelium and stroma regions." (PMID 24339876, 2013). "Association between haplotypes of rs1970801 and rs1434536 in BMPR1B with endometriosis and CA125 level in patients." (PMID 24339876, 2013). "Such LD map suggested a more rigid genetic pattern at rs1970801 and rs1434536 of BMPR1B preserved through generations in endometriosis patients." (PMID 24339876, 2013). "Genotype and allele distributions of SNPs surrounding miRNA target site of BMPR1B in endometriosis patients and controls." (PMID 24339876, 2013). "Single-nucleotide polymorphisms rs1970801, rs1434536, and rs11097457 near the miR-125b binding site in BMPR1B were genotyped by Taqman assay on 193 endometriosis patients and 202 healthy controls." (PMID 24339876, 2013). "Haplotype frequencies were analyzed for two disease-related SNPs within BMPR1B to confirm participation of this gene in endometriosis pathogenesis." (PMID 24339876, 2013). "Our study indicates involvement of epigenetic regulation in endometriosis development via miRNA-facilitated repression of BMPR1B, suggesting therapeutic potential of the BMP signaling pathway in endometriosis." (PMID 24339876, 2013). "SNPs of BMPR1B within and next to the miR-125b binding site manifested strong correlation with endometriosis development in a Taiwanese cohort." (PMID 24339876, 2013). "BMPR1B was correlated with cell proliferation, suggesting that it may play a role in protecting against endometriosis progression." (PMID 32315343, 2020). "Endometriosis epithelium and stroma cells may possess opposite innate efficacy to express BMPR1B and CA125." (PMID 24339876, 2013). "Our study of BMPR1B in endometriosis may help understanding of disease etiology and provide new perspectives on prognosis and therapeutic approaches." (PMID 24339876, 2013). "On the other hand, patients with the variant allele of rs1434536 could maintain relatively unaffected levels of BMPR1B, CA125, and IL-1β, offsetting elevation of miR-125b level presented in endometrium cells, which may prevent endometriosis." (PMID 24339876, 2013). "BMPR1B, a member of the bone morphogenic protein (BMP) receptor family of transmembrane serine/threonine kinase, belongs to the transforming growth factor-β (TGF-β) superfamily, whose members are dynamically expressed in the endometrium during menstruation, pregnancy, and endometriosis." (PMID 24339876, 2013).
lung carcinoma (3 papers, 2012 to 2021). "The 3′UTR of BMPR1B contains a binding site for miR-125b that is disrupted by both a somatic mutation that was identified in lung cancer (chr4:g.96075969G>T) and a germline SNP (rs1434536)." (PMID 23091610, 2012). "A 3′UTR somatic mutation in BMPR1B identified in a lung cancer patient disrupts the specific target site of miR-125b that has previously been investigated for its role in cancer." (PMID 23091610, 2012). "BMP7 signaling via BMPR1A and BMPR1B could inhibit the proliferation of lung cancer cells." (PMID 34036102, 2021).